INS (insulin)
Diseases named in the same sentence as INS in open-access papers (continued):
Sharing a sentence is not in itself a finding about the gene and the disease.
Obesity (continued). "Maternal hyperglycaemia has a profound impact on the developing foetus and increases the risk of developing abnormalities like obesity, impaired glucose tolerance and insulin secretory defects in the post-natal life." (PMID 30858575, 2019). "Physical inactivity, that can be both a cause and a consequence of obesity, is known to be associated with decreased insulin sensitivity, reduced postprandial lipid metabolism, decreased muscle mass, and obesity." (PMID 31423716, 2019). "In this study we used a model of diet-induced obesity (60% calories from fat), as it recapitulates many of the obesity-associated conditions in humans, such as adipose tissue remodeling, insulin resistance and hepatic steatosis." (PMID 31379826, 2019). "Despite promising evidence from observational studies, evidence from randomized controlled trials (RCTs) regarding vitamin D effects on cardiovascular risk factors such as obesity, insulin sensitivity, or serum lipids is inconsistent." (PMID 31416155, 2019). "Obesity, fatty liver and dysregulated insulin action are strongly associated and are currently a worldwide health problem." (PMID 31836013, 2019). "Reducing thrombin action was found to directly improve insulin sensitivity in leptin resistant obese mice, suggesting a causal role for prothrombrotic processes in obesity-related insulin resistance." (PMID 30874564, 2019). "It was originally found in Otsuka Long-Evans Tokushima rats and associated with obesity and insulin sensitivity in rats and humans." (PMID 30915034, 2019). "Elevated vaspin concentrations in serum are associated with obesity and alterations in insulin sensitivity in humans, even in infancy." (PMID 30325336, 2019). "Although both were associated with salivary CRP, insulin, and adiponectin, leptin was unique for obesity evaluated by waist circumference." (PMID 31236292, 2019). "Heterozygous deletion of SOD2 has been shown to cause impaired insulin secretion in a mice model of obesity." (PMID 31781116, 2019). "On the one hand, we find evidence that the differential methylation of the insulin-related CpG sites together explained up to 16.9% of the association between obesity and insulin levels." (PMID 31197173, 2019). "These have led to discovery of DNA methylation changes that are associated with many genes and pathways related to obesity and its comorbidities, including appetite control, insulin signaling, immunity, and inflammation." (PMID 31555578, 2019). "Other miRNAs are likely to be regulated by the same cascade downstream of both insulin and leptin, contributing to the correlation between obesity/IR and cancer risk." (PMID 31207998, 2019). "Even so, the growing body of epidemiologic evidence for an association between insulin and cancer risk and progression begs the question of what explains the potential mechanistic link between obesity, hyperinsulinemia, and cancer." (PMID 31867105, 2019). "These mice become insulin resistant due to leptin deficiency and develop severe obesity, moderate hyperglycemia with high insulin release capacity and marked adiposity." (PMID 30732594, 2019). "IL-6 stimulates hepatic lipogenesis, and is associated with obesity, impaired insulin signaling, and altered insulin sensitivity by activating key steps in the insulin signaling pathway." (PMID 31921154, 2019). "Recent studies aimed at ameliorating cardiometabolic disorders associated with obesity have highlighted protein tyrosine phosphatase 1B (PTP1B) as a potential target to improve not only insulin sensitivity, but also endothelial dysfunction." (PMID 30679477, 2019). "Strengthening the relation of obesity and reduced insulin sensitivity are the observations that weight gain reduces insulin sensitivity while weight loss increases it." (PMID 31474943, 2019). "Obesity is associated with inflammatory macrophages in insulin responsive tissues and the resulting inflammatory response is a major contributor to insulin resistance." (PMID 31787760, 2019).
Obesity (continued). "The authors of this study additionally demonstrated that in obesity, myeloid specific Irs2−/− mice exhibit impaired insulin sensitivity, associated with more pro-inflammatory (F4/80+CD11c+CD206−) and less anti-inflammatory (F4/80+CD11c−CD206+) ATMs." (PMID 31497027, 2019). "Mice deficient in miR-378-3p and miR-378a-5p became resistant to obesity due to high-fat diet and showed improved fatty acid metabolism targeting carnitine O-acetyltransferase, enhancing oxidative efficiency of insulin-sensitive tissues." (PMID 31207998, 2019). "Reduced dietary salt helps lower hypertension, less dietary sugar lowers risk of cardiovascular disease and obesity, and reducing proportion of dietary carbohydrates lowers post-meal insulin secretion and insulin resistance." (PMID 30678194, 2019). "The molecular mechanisms underlying the relationship between obesity and breast carcinogenesis involves estrogens, insulin, leptin, adiponectin, and inflammatory cytokines." (PMID 31380268, 2019). "Bioenergetic failure has been associated with the loss of skeletal muscle insulin sensitivity in obesity and uraemia, as well as in the development of kidney disease and its sarcopenic complications." (PMID 31195596, 2019). "Vitamin D plays an essential role in the regulation of glucose homeostasis, insulin secretion mechanisms, and inflammation associated with obesity." (PMID 30881343, 2019). "To that end, we show here that insulin increases mitochondrial glucose oxidation and augments cell division in cells from obesity-associated tumors, while obesity-independent cell lines show no alteration of substrate preference." (PMID 31188872, 2019). "Using mendelian randomization approaches, Paul Brennan and colleagues reveal an association between 12 obesity-related factors, including insulin and the development of renal cell carcinoma." (PMID 30605491, 2019). "Several studies have confirmed that ARHGEF11 affects the metabolism of glucose and fatty acids through the insulin signaling pathway and acts as a key determinant of metabolism- and obesity-associated pathologies." (PMID 31612150, 2019). "We think that tissue-specific responses to insulin are highly relevant for the bone field with respect to understanding the pathophysiology of obesity and T2D-associated bone disease." (PMID 31749085, 2019). "Insulin signaling is closely associated with a variety of diseases such as obesity, hyperglycemia, and metabolic syndrome." (PMID 31035366, 2019). "High-carbohydrate diets (50% to 65% of calories from carbohydrates) have been associated with increased insulin resistance and obesity and shifting benign fatty liver toward NASH." (PMID 31779112, 2019). "High expression of Lpin1 in adipose tissue and skeletal muscle can cause obesity, but the insulin sensitivity is different in the two tissues." (PMID 30902099, 2019). "Obesity is an independent risk factor for several hormonal abnormalities, such as increased concentrations of testosterone and insulin, and reduced concentrations of the sex hormone-binding globulin, which inevitably influences the menstrual cycle." (PMID 30717736, 2019). "Increased insulin levels have been regarded as a crucial factor for the poor prognosis of obesity-associated cancer." (PMID 31719636, 2019). "Together, these results suggest that the Nlrp1b1 allele attenuates the alterations in glucose metabolism associated to obesity by improving insulin sensitivity." (PMID 31554824, 2019). "Serum levels of adiponectin decrease with obesity and are positively associated with insulin sensitivity." (PMID 31141089, 2019). "Gestational hyperglycaemia increases the risk for developing neurodevelopmental problems, increased risk of obesity, impaired glucose tolerance, impaired insulin secretion, hypertension and cardiovascular complications in post-natal life." (PMID 30858575, 2019).
Obesity (continued). "NAFLD is strongly associated with obesity, insulin resistance, and subclinical systemic inflammatory state; lifestyle modification, weight loss, insulin-sensitizing agents, and bariatric surgery are therefore commonly recommended treatments." (PMID 31697646, 2019). "IL-6 is the most widely studied exercise-regulated cytokine and is associated with obesity and insulin resistance; but it is also highly produced and secreted after exercise, enhancing insulin action and other metabolic processes." (PMID 31590286, 2019). "Obesity and perturbed metabolism are associated with altered levels of insulin/IGFs, inflammatory cytokines, and important metabolic fuels." (PMID 30809194, 2019). "Recent reports showed that obesity should play a major role in the pathogenesis of PCOS through the insulin, leptin and endocannabinoid receptor, and by an association between insulin receptor polymorphism and PCOS was observed." (PMID 30635060, 2019). "The importance of the dietary n-6/n-3 ratio in diverse chronic health conditions such as obesity-linked inflammation and insulin dysregulation was evidenced in Sprague-Dawley rat models and human studies." (PMID 30897169, 2019). "Obesity is associated with dysregulation of multiple biologic pathways involving adipokines, insulin and insulin-like growth factor (IGF) signaling, endogenous sex hormone levels, and chronic inflammation." (PMID 30867005, 2019). "Another study reported that female gender, age, poor glycemic control, obesity, diabetic complications, and insulin therapy in the Chinese population were risk factors for T2DM when combined with depression." (PMID 31391021, 2019). "A possible mechanism on the involvement of body fat on CRC risk is based on obesity-related hormone levels, such as insulin, estrogens, and IGF-1, promoting carcinogenesis and counteracting apoptotic cell death." (PMID 31207998, 2019). "Whatever the origin of obesity-associated diabetes, there is a failure in insulin production and/or the secretory capacity of β-cells." (PMID 31178685, 2019). "Conversely, another study indicated that TLR3-deficient mice with HFD-induced obesity exhibit increased glucose tolerance and serum insulin and decreased serum levels of very low-density lipoproteins and triglycerides (TG)." (PMID 31582899, 2019). "Obesity is certainly associated with a series of endocrine and metabolism alterations, in particular the metabolism of sex hormones, insulin, and Igf (insulin growth factor), adipokines (hormones produced by adipose tissue), as well as inflammation." (PMID 31456748, 2019). "Several miRNAs have been implicated in the control of both insulin signaling and glucose metabolism at multiple levels and their expressions were associated with obesity." (PMID 31040824, 2019). "Suggested mechanisms for the association of obesity and obesity-related traits with meningioma risk include chronic inflammation, and increased adipokine-mediated signalling, insulin signalling and insulin-like growth factor (IGF) signalling." (PMID 30670737, 2019). "Obesity and insulin increase inflammation and have direct and indirect causal effects in breast cancer, including increased aromatase activity." (PMID 31888528, 2019). "Adiponectin is an insulin-sensitizing hormone secreted from the adipose tissue and is negatively associated with obesity and T2D in epidemiological studies." (PMID 30816311, 2019). "The resistance of PTP1B−/− mice to obesity and improved insulin sensitivity have led scientists to investigate the underlying molecular basis." (PMID 31319588, 2019). "Although achievement of normoglycemia is one of the primary objectives in children with type 1 diabetes, intensive insulin treatment is often associated with higher insulin doses and an increase in weight and obesity." (PMID 30849076, 2019).
Obesity (continued). "Obesity-induced skeletal muscle inflammation is a major contributor of skeletal muscle loss/atrophy and is implicated in metabolic complications such as insulin resistance." (PMID 31312114, 2019). "Since obesity is commonly linked with insulin resistance, weight loss should restore insulin sensitivity." (PMID 31213970, 2019). "Specifically, rising degrees of obesity were associated with greater fasting and prandial adipose IR as well as with lower whole-body insulin sensitivity." (PMID 30637483, 2019). "The results showed that follistatin suppressed obesity caused by a high-fat diet and increased insulin sensitivity, energy expenditure, and subcutaneous fat browning." (PMID 31365569, 2019). "We have shown that mice over expressing human IGFBP-2 have a reduced susceptibility to obesity and also improved insulin sensitivity." (PMID 30392760, 2019). "Differential DNA methylation is further associated with obesity, which is an important driver of the T2D risk and also precedes the increase in glucose and insulin level in persons developing T2D8." (PMID 31197173, 2019). "NAFLD is independently associated with T2DM, obesity and metabolic syndrome, and the accumulation of fatty acid in the liver impairs insulin sensitivity." (PMID 30923554, 2019). "It is generally known that obesity is associated with increased secretion of mediators that reduce insulin-mediated glucose uptake and insulin sensitivity, such as TNF-α, IFN-γ, and IL-1β." (PMID 31772933, 2019). "Obesity is a pathological state associated with dysregulated inflammatory and metabolic mediators, including blood glucose, insulin, IGF-1, and leptin." (PMID 31835454, 2019). "In conclusion, our large-scale EWAS and replication identifies nine differentially methylated sites associated with fasting glucose or insulin, and shows that differential methylation explains part of the association between obesity and insulin metabolism." (PMID 31197173, 2019). "Hypogonadism associated with obesity is not only associated with low testosterone, but also high estrogen, high insulin, leptin resistance among other hormonal abnormalities." (PMID 31052376, 2019). "During a healthy pregnancy, body fat increases followed by a reduction of insulin sensitivity and the elevation of circulating cytokines that are thought to drive obesity-associated metabolic inflammation." (PMID 31484413, 2019). "This study has been supported by previous work conducted among 1198 individuals from the Bellville-South region in Cape Town, in which GGT levels were independently associated with insulin sensitivity and obesity." (PMID 31100911, 2019). "AHI1 is required for both cerebellar and cortical development and has been previously shown to be associated with fat development and obesity via regulating insulin signaling." (PMID 31737448, 2019). "Other research from the United States supports the claim that access to fast-food restaurants is associated with obesity among adults, excess weight gains over time as well as insulin resistance." (PMID 30669996, 2019). "DM and obesity are both associated with selective impairment of some insulin signaling pathways (e.g., the PI3K pathway) that reduce nitric oxide availability and cause a compensatory hyperinsulinemia." (PMID 30962800, 2019). "The close association between obesity, peripheral tissue resistance to insulin action, and T2D is reflected in the frequently used descriptive term “diabesity”." (PMID 30678194, 2019). "Overall, these observations suggest that the impaired skin function associated with obesity is due, at least in part, to cutaneous insulin resistance and consequent decreases in keratin expression." (PMID 31581253, 2019). "Increased levels of long-chain ACs in plasma and tissues have been described in association with obesity and insulin resistance, but also after weight loss and exercise paralleling increases in systemic insulin sensitivity." (PMID 31349613, 2019).
Obesity (continued). "In animal studies, overexpression of FOXO1 in both the hypothalamus and pancreas causes obesity, glucose intolerance and decreased insulin sensitivity." (PMID 31156786, 2019). "The association between body temperature and insulin persisted after adjustment for obesity markers in women and to a lesser degree in men, a finding also reported elsewhere." (PMID 30250242, 2019). "Oxidative stress and inflammation in the lung increased the systemic pool of pro-inflammatory and end-oxidation products that reduce insulin sensitivity and cause other metabolic abnormalities-associated to obesity." (PMID 39450269, 2019). "Obesity and chronic hyperglycemia are risk factors in developing metabolic derangements (i.e., reduced insulin sensitivity)." (PMID 31354623, 2019). "It has been shown in obese children that greater degree of obesity is associated with greater deposition of lipids within muscle and liver and that increasing obesity is associated with lower insulin sensitivity of adipose tissue itself." (PMID 31474943, 2019). "Leucine supplementation affected the susceptibility to high-fat diet-induced obesity and promoting insulin signaling in insulin-target tissues in rats." (PMID 31847151, 2019). "Metabolic GO terms associated with this gene include ‘gluconeogenesis’ and ‘positive regulation of insulin secretion,’ and it has been linked with human obesity." (PMID 31412766, 2019). "Obesity-targeting weight loss interventions have produced favorable changes in fasting insulin, glucose and HOMA-IR concentrations." (PMID 31555578, 2019). "The differential methylation explains at least 16.9% of the association between obesity and insulin." (PMID 31197173, 2019). "Bmal1-knockout mice lose the rhythms in insulin and are locked into the trough stage of insulin secretion, and experience increased risk of obesity under high-fat diet." (PMID 31555652, 2019). "Recent metabolomic studies identified correlations between lysophosphatidylcholine (LPC) (lysoPC C17:0, 18:1, and 18:2) and obesity, whereas sphingomyelins (C18:1) and dhCers were associated with a pre-diabetic insulin state." (PMID 31771303, 2019). "PPARG down-regulation leads to impaired capacity of adipose tissue to accumulate lipids, which in turn provokes ectopic lipid accumulation, insulin resistance and other obesity-associated comorbidities." (PMID 30642114, 2019). "A loss-of-function animal study showed that NLRP3-, ASC-, and caspase-1-deficient mice are protected from HFD-induced obesity and show improved glucose tolerance and insulin sensitivity." (PMID 31582899, 2019). "In both mouse models and humans, the increase of beige adipocyte population, also called WAT browning, is associated with certain metabolic benefits, such as reduced obesity and increased insulin sensitivity." (PMID 31805721, 2019). "Unfortunately, many patients with PCOS have underlying genetic predispositions for obesity and related reduced insulin sensitivity, which can make weight loss difficult." (PMID 31367382, 2019). "Obesity exacerbates aging-associated inflammation by impairing insulin responsiveness and contributes to the pathophysiology of diseases frequently observed in the elderly." (PMID 30915034, 2019). "cDC accumulation during obesity has been shown to be attenuated in Ccr7−/− mice and associated with decreased adipose tissue inflammation and lowered fasting glucose and insulin levels, suggesting that DCs are only partially CCR7-dependent." (PMID 31191541, 2019). "This change induces higher adiposity and insulin insensitivity, which resembles obesity-associated metabolic syndrome traits." (PMID 31484413, 2019). "On the other hand, obesity was found to cause an increase in the chance of need for insulin supplementation." (PMID 31856288, 2019).